UPF3A (UPF3A regulator of nonsense mediated mRNA decay)
Description:
Involved in nonsense-mediated decay (NMD) of mRNAs containing premature stop codons by associating with the nuclear exon junction complex (EJC) and serving as link between the EJC core and NMD machinery. Recruits UPF2 at the cytoplasmic side of the nuclear envelope and the subsequent formation of an UPF1-UPF2-UPF3 surveillance complex (including UPF1 bound to release factors at the stalled ribosome) is believed to activate NMD. However, UPF3A is shown to be only marginally active in NMD as compared to UPF3B. Binds spliced mRNA upstream of exon-exon junctions. In vitro, weakly stimulates translation.
Synonyms: RENT3A; UPF3; HUPF3A
Tractability: Antibody: its Gene Ontology location is reachable by antibodies, with high confidence. PROTAC: ubiquitination databases record sites on it; its protein half-life has been measured.
Gene: Protein-coding gene on chromosome 13 (114,281,568 to 114,305,817, forward strand). Ensembl gene ENSG00000169062.
Subcellular location: Nucleus; Cytoplasm
Subcellular location (Human Protein Atlas): Nucleoplasm; Plasma membrane; Vesicles; Basal body; Primary cilium; Primary cilium tip
Pathways (Reactome):
Developmental Biology: Regulation of expression of SLITs and ROBOs
Metabolism of RNA: Nonsense Mediated Decay (NMD) enhanced by the Exon Junction Complex (EJC)
Gene Ontology:
Molecular function: mRNA binding; protein binding; protein sequestering activity; telomeric DNA binding; nucleic acid binding
Biological process: negative regulation of nuclear-transcribed mRNA catabolic process, nonsense-mediated decay; nuclear-transcribed mRNA catabolic process, nonsense-mediated decay; positive regulation of translation; RNA surveillance
Cellular component: exon-exon junction complex; nucleoplasm; cytoplasm; cytosol; nonsense-mediated decay complex; nucleus; neuron projection
Genetic constraint (gnomAD): Loss-of-function variants: 35 observed, 38.74 expected, observed/expected ratio (o/e) 0.9, 90% interval 0.69 to 1.2. The upper end of that interval is the gene's LOEUF score, 1.2, which puts it in group 5 of 6, group 1 being the genes least tolerant of losing a copy. Missense variants: 488 observed, 465.29 expected, observed/expected ratio (o/e) 1.05, 90% interval 0.97 to 1.13. Synonymous variants: 214 observed, 174.55 expected, observed/expected ratio (o/e) 1.23, 90% interval 1.1 to 1.37.
Homologues: Orthologues: chimpanzee UPF3A (99% identical), macaque UPF3A (93% identical), pig UPF3A (67% identical), mouse Upf3a (63% identical), rat Upf3a (62% identical), guinea pig UPF3A (60% identical), tropical clawed frog upf3a (59% identical), dog UPF3A (52% identical), zebrafish upf3a (51% identical), Drosophila melanogaster Upf3 (26% identical), Caenorhabditis elegans smg-4 (22% identical). Paralogues in human: UPF3B (45% identical).
Diseases named in the same sentence as UPF3A in open-access papers:
UPF3A is named in the same sentence as 26 diseases in open-access papers, as found by Europe PMC text mining. Sharing a sentence is not in itself a finding about the gene and the disease. The quoted sentences say what the papers report.
colorectal cancer (3 papers, 2020 to 2024). A primary or metastatic malignant neoplasm that affects the colon or rectum. "We show for the first time that UPF3A frameshift mutations are frequent in MSI colorectal cancer cell lines, primary cancers and adenomas but also occur in MMR-deficient tumors of other organs, albeit at lower frequency." (PMID 32718059, 2020). "The high UPF3A mutation frequency in MSI colorectal carcinomas was independently confirmed in an additional set of 78 CRCs (validation set)." (PMID 32718059, 2020). "Therefore, the observed high frequency of UPF3A mutations we found in MSI colorectal cancer might actually result from a selective pressure to enhance NMD efficiency." (PMID 32718059, 2020). "Overall, UPF3A represents the only NMD-related gene genetically altered in more than 50% of MSI colorectal cancer cell lines and MSI primary colorectal tumors." (PMID 32718059, 2020). "To determine if the mutational status affects UPF3A expression, we performed Western Blot analyses of protein extracts from 30 MSI colorectal cancer cell lines that differ in their UPF3A allele status." (PMID 32718059, 2020). "Additionally, UPF3a may contribute to the aggressive nature and unfavorable prognosis of colorectal cancer." (PMID 39668816, 2024). "UPF3A could not be detected in cell lysates of all MSI colorectal cancer cell lines with homozygous A9 cMNR frameshift mutations (UPF3A−/−; 6/30, 20%)." (PMID 32718059, 2020).
Intellectual disability (3 papers, 2021 to 2022). "UPF3A and its paralog UPF3B antagonistically regulate NMD, and both have been implicated in ASDs, intellectual disability, and schizophrenia." (PMID 36618441, 2021). "In addition, they may also help to better understand the link between UPF3B and intellectual disability and which domains of UPF3A modulate the severity of the disease and may therefore be potential targets for therapy." (PMID 35451084, 2022).
breast carcinoma (2 papers, 2019 to 2024). "TGLI1 and STAT3 transcription factors interact to co-regulate target genes, Cep70, UPF3A, and RRas2, to mediate aggressive phenotypes in breast cancer." (PMID 39768178, 2024). "KCZ+BZA co-treatment reduced protein expression of Cep70, UPF3A, and RRas2, shedding new light on the underlying mechanism of combination treatment in HER2-enriched breast cancer and TNBC." (PMID 39768178, 2024).
amyotrophic lateral sclerosis (1 paper, 2020). Amyotrophic lateral sclerosis (ALS) is a neurodegenerative disease characterized by progressive muscular paralysis reflecting degeneration of motor neurons in the primary motor cortex, corticospinal tracts, brainstem and spinal cord. "It has also been reported that UPF3A is decreased in cells of patients with amyotrophic lateral sclerosis." (PMID 32718059, 2020).
colon cancer (1 paper, 2020). "How altered UPF3A function might contribute to such diverse disease pathologies such as neuronal defects and colon cancer is difficult to reconcile." (PMID 32718059, 2020). "To analyze UPF3A-specific effects, we generated a genetically modified MSI colon cancer cell line KM12-UPF3A (UPF3A−) that confers doxycycline (dox)-regulated wild type (WT) UPF3A expression in an isogenic background." (PMID 32718059, 2020).
colorectal adenoma (1 paper, 2020). An adenoma that arises from the colon or rectum. "A high frequency of cMNR frameshift mutations in the UPF3A gene was found in MSI CRC cell lines (67.7%), MSI colorectal adenomas (55%) and carcinomas (63%)." (PMID 32718059, 2020).
embryonic carcinoma (1 paper, 2023). "A detailed analysis of UPF3A functions in HEK293 cells, Hela cells, mouse pluripotent cells (P19: embryonic carcinoma cell), somatic cells, and major organs, such as olfactory bulbs and testes, identified a novel function of UPF3A as a general and strong NMD repressor in mammals." (PMID 36997282, 2023).
ovarian carcinoma (1 paper, 2023). A malignant neoplasm originating from the surface ovarian epithelium. "On the other hand, the model composed of GALNT9, UPF3A, WARS, and LDB2 incorrectly identified 1 out of 16 cancer cases (6.25%: ovarian cancer)." (PMID 37794510, 2023).
sarcopenia (1 paper, 2022). Progressive decline in muscle mass due to aging which results in decreased functional capacity of muscles. "The top three identified hub genes are UPF3A, CSTB and PEA15, which were all affiliated to common genes of sarcopenia and proliferating myoblasts of T2DM." (PMID 35271662, 2022).
tumor (4 papers, 2018 to 2024). "In this context, loss of UPF3A expression might provide a growth advantage for dMMR CRC tumor cells." (PMID 32718059, 2020). "In contrast, tumor tissues that carry UPF3A mutations have lost UPF3A protein expression." (PMID 32718059, 2020). "However, we did not detect any biallelic UPF3A mutations in primary tumor tissues." (PMID 32718059, 2020). "Expression levels for NMD-related factors (UPF1, UPF2, UPF3A, UPF3B, SMG1, SMG2, SMG6, and SMG7) were calculated from microarray-derived datasets of primary tumor samples (n = 40 MSI, n = 48 MSS) and matched normal colon samples (n = 95)." (PMID 30228267, 2018). "Furthermore, it was reported UPF1 acts a tumor suppressive gene in HCC, but, the role played by UPF3A, in the pathogenesis of HCC, has not been well studied." (PMID 31856847, 2019).
neurodevelopmental disorder (3 papers, 2022). A behavioral and cognitive disorder with onset during the developmental period that involves impaired or aberrant development of intellectual, motor, or social functions. "For instance, loss-of-function mutations in UPF2, UPF3B, SMG8 and SMG9 genes, and CNVs targeting UPF2, UPF3A, SMG6, EIF4A3, RNPS1 and RBM8A genes, have been implicated in a variety of neurodevelopmental disorders, including DD, ID, ADHD and TAR syndrome." (PMID 35327467, 2022).
neurological disorders (1 paper, 2022). "A better understanding of the extent to which UPF3A functions synergize or antagonize those of UPF3B is also necessary to understand the basis of UPF3B‐caused human neurological disorders." (PMID 35451102, 2022).
UPF3A also shares sentences with these, for which no sentence is quoted: cancer (4 papers); adenoma (2); infection (2); bladder carcinoma (1); childhood onset schizophrenia (1); colorectal tumors (1); developmental delay (1); HIV-1 infection (1); Infertility (1); melanoma (1); pancreatic cancer (1); schizophrenia (1); type 2 diabetes (1); virus infection (1).